MIR1302-8 (microRNA 1302-8)
Synonyms: hsa-mir-1302-8; MIRN1302-8
Gene: MicroRNA gene on chromosome 9 (97,363,554 to 97,363,681, reverse strand). Ensembl gene ENSG00000221269.
Homologues: Orthologues: chimpanzee ptr-mir-1302-8 (100% identical). Paralogues in human: MIR1302-1 (72% identical), MIR1302-6 (38% identical).